STAT3 (signal transducer and activator of transcription 3)
Diseases named in the same sentence as STAT3 in open-access papers (continued):
Sharing a sentence is not in itself a finding about the gene and the disease.
breast cancer (continued). "In addition, the Src/Stat3 signaling pathway plays a crucial role in controlling JAB1 transcription in breast cancer cells, and treatment with Stat3 and Src-targeting siRNAs noticeably reduces JAB1 promoter function and expression." (PMID 38683453, 2024). "Notably, high levels of tyrosine-phosphorylated signal transducer and activator of transcription 3 (p-STAT3) are found to be constitutively activated in a number of malignancies, including almost half of all human breast cancers and act as oncogenic transcription factors." (PMID 39064812, 2024). "Comparative pathway analysis identified the GP6, STAT3 and G protein-coupled receptor signaling pathways to be the top three most significantly dysregulated pathways in both basal-like breast cancer cell lines, MDA-MB-468 and BT-549, but not in the Her2-enriched HCC-1954 cell line." (PMID 39001513, 2024). "Whether tGLI1 and GP130, an upstream regulator of STAT3, are frequently co-overexpressed and concurrently activated in breast cancer has not yet been investigated." (PMID 39768178, 2024). "Additionally, let-7a-5p maturation is inhibited by hnRNPA1, thus forming a let-7a-5p/Stat3/hnRNPA1 negative feedback pathway in breast cancer cells." (PMID 38785973, 2024). "The interactions of the mTOR cascade with STAT-mediated signaling (e.g., in immunity), and the roles attributed to STAT3 and STAT1 in promoting PD-L1 expression, have led us to inquire in depth about the potential involvement of STAT3 and STAT1 in PD-L1-mediated effects in breast cancer cells." (PMID 37830552, 2023). "In this study, we did not investigate whether changes in IL6/JAK/STAT3 and OXPHOS signaling explain the increased risk of mammary cancer recurrence in socially isolated rats." (PMID 36980301, 2023). "However, the effect of VaM on STAT3 signaling in breast cancer cells has not been extensively studied." (PMID 37569363, 2023). "Whereas Y705 phosphorylation has affected all pro-metastatic functions of TME-stimulated HR+/HER2− breast cancer cells, the complete absence of STAT3—with its S727 phosphorylation site and other regulatory domains —had no influence on tumor-promoting activities, of any kind." (PMID 37190183, 2023). "To study the role of the alternatively-spliced STAT3 isoforms in cancer cells we silenced the mRNA expression of either STAT3α (si-STAT3α), the main isoform, or STAT3β (si-STAT3β) or both (si-STAT3α+β) in MDA-MB-231 breast cancer cells using specific siRNA molecules." (PMID 37097001, 2023). "Additionally, in the human HER2-overexpressing breast cancer cell lines BT-474, SKBR3, and MDA-MB-453, apigenin triggers cell apoptosis by suppressing JAK/STAT3 signaling and decreasing nuclear translocation of STAT3." (PMID 38203418, 2023). "However, cell proliferation and cell cycle were not significantly different in 4T1 breast cancer cells after silencing STAT3 compared with the control group." (PMID 38067351, 2023). "Some studies indicate that immune cells and CAFs secrete IL-6 to activate JAK/STAT3 and PI3K/AKT signaling pathways in tumor cells, which results in the degradation of ERα through the ubiquitin protease pathway, leading to tamoxifen resistance in breast cancer." (PMID 37900137, 2023). "In addition, not only STAT3 but also the NOTCH1 signaling pathway is known to be involved in the acquisition of chemotherapy resistance in head and neck squamous cell carcinoma (HNSCC), breast cancer, and gastrointestinal cancer." (PMID 37373457, 2023). "Considering the reported roles of STAT3 in mitochondrial function and oxidative phosphorylation, we wanted to test whether PRRG4 can activate STAT3 via Src especially considering that Src and STAT3 are commonly involved in breast cancer." (PMID 38102641, 2023).
breast cancer (continued). "In line with this notion, the antiproliferative effect of a derivative of the type 1 oxa-3-azaspiro[5.5]undecane has been observed through the modulation of the JAK2/STAT3 pathway in hepatocellular carcinoma and breast cancer cells, regardless of estrogen receptor expression status." (PMID 37299000, 2023). "The function of nuclear HER2 could be directed by STAT3, which recruits HER2 to activate the expression of miRNA-21 that in turn down-regulates the expression of the metastasis suppressor protein programmed cell death 4 (PDCD4) in breast carcinoma." (PMID 36459290, 2023). "ROCK regulating the phosphorylation of STAT3 to promote macrophage polarisation is not a new concept, and has previously been reported in chronic graft versus host disease, hepatocellular carcinoma and breast cancer." (PMID 36178087, 2022). "Furthermore, it has been reported that LEP in breast cancer models, via JAK2/STAT3 pathway, promotes cell cycle progression by increasing the expression of cdk2 and cyclin D1 levels, thus inducing hyperphosphorylation and subsequent inactivation of the cell cycle inhibitor Rb." (PMID 36291602, 2022). "Targeting the leptin-STAT3-FAO axis might potentiate robust anti-tumor CD8 + T immune killing effect, in addition to inhibiting cancer stem cells (CSCs) and chemo-resistant tumor cells in breast cancer." (PMID 35701840, 2022). "In Palbociclib-resistant breast cancer cells, PARP inhibition combined with a STAT3 specific inhibitor re-sensitized cells to the agent, suggesting that concurrent targeting of DDR mechanisms and the IL6/STAT3 pathway could effectively treat acquired resistance to Palbociclib." (PMID 36499000, 2022). "Considering the effect of SOST on breast cancer cell proliferation and the presence of SOST in the cytoplasm, we speculate that SOST may activate the RAS and TGF-β signaling pathways by interacting with intracytoplasmic transcription factors, such as STAT3." (PMID 36581888, 2022). "Interestingly, novel JAK2/STAT3 inhibitor, WP1066, can penetrate the blood-brain-barrier, suppress brain metastases in vivo, and prolong overall survival in mice inoculated with brain-trophic TNBC breast cancer cells via an intracardiac injection." (PMID 35371975, 2022). "LncRNA ZNFX1 antisense RNA 1 (ZFAS1) levels were downregulated in breast cancer tissues, and silencing ZFAS1 expression obviously promoted the cell proliferation of MDA-MB-231 by activating the signal transducer and activator of the transcription 3 (STAT3) pathway." (PMID 36613528, 2022). "Furthermore, STAT3 and p300, which both act as PR co-activators, have recently been identified as mechanotransducers in breast cancer cell lines, indicating a further link between PGR and stiffness in breast cancer." (PMID 35617163, 2022). "In breast cancer, disintegrin and metalloproteinase domain-containing protein 12 (ADAM12) is one of the members of MMP family, which its overexpression could increase angiogenesis through epidermal growth factor receptor (EGFR)/STAT3/AKT in BC." (PMID 35499045, 2022). "Hence, we cannot exclude that the downregulation of the STAT3 pathway could also account, at least partly, for the induction of PCD-1 and PCD-II in carnosol-treated breast cancer cells." (PMID 35712465, 2022). "There is limited clinical trial evidence to support the use of STAT3 inhibitors as a breast cancer therapeutic, although one current early-phase trial is currently evaluating the efficacy of an oral STAT3 inhibitor TTI-101 for a range of late-stage cancers including breast cancer (NCT03195699)." (PMID 35053592, 2022). "Interestingly, in MCF-7 breast cancer cells, LEP has been demonstrated to be able to sustain, in a dose-dependent manner, the cancer cell immortalization by upregulating the expression of Human Telomerase Reverse Transcriptase (hTERT) via STAT3 dimerization." (PMID 36291602, 2022).
breast cancer (continued). "However, recent studies showed that STAT3 is activated by Y727 phosphorylation independent of Y705 status in trible negative breast cancer, thereby attenuating the effect of STAT3 inhibitor ‘Stattic’." (PMID 36479072, 2022). "Accordingly, highly active STAT3 signaling may be a negative prognostic indicator in breast cancer patients, although epidemiological evidence remains uncertain." (PMID 35053592, 2022). "However, the activation of STAT3 does not appear to be an independent marker of breast cancer prognosis." (PMID 36010693, 2022). "We already mentioned that CYP3A4 participates in breast cancer progression by stimulating angiogenesis through VEGF activation and by promoting cancer cell proliferation through the activation of PI3 kinase–AKT and STAT3 pathways, in part via the synthesis of (+/−)-14,15-EET." (PMID 36359206, 2022). "Importantly, we found that breast cancer-derived CXCL1-3 and CXCL8 bind to the receptor CXCR2 and activate the ERK1/2 signaling pathway to initiate the expression of LIF by activating transcription factors NF-κB and Stat3 in CAAs in paracrine manner." (PMID 35280694, 2022). "Notably, STAT3 has also been reported to be important for regulating lysosomal membrane permeabilization (LMP) and lysosome-dependent cell death (LDCD) during post-lactational regression of the mammary gland epithelium and in breast cancer cells." (PMID 35053502, 2022). "Mechanistically, SHOX2 activates signal transducer and activator of transcription 3 (STAT3) and recruits it to the WASF3 promoter, where STAT3 cooperates with SHOX2 to form a functional immunocomplex to promote WASF3 transcriptional activity in breast cancer cells." (PMID 34465361, 2021). "RBP NONO promotes breast cancer cell growth by increasing the stability of STAT3 mRNA." (PMID 33461173, 2021). "However, our study using both non-triple and triple negative cell lines suggested that STAT3 contributed to breast cancers with specific post-transcriptional modification." (PMID 34335938, 2021). "In particular, glioblastoma, breast cancer, colon cancer, melanoma, lung adenocarcinoma, head and neck cancer, pancreatic cancer, liver cancer, and prostate cancer cohorts showed the most significantly (p < 0.001) elevated CDK2, CDK4, CDK6, and STAT3 expressions." (PMID 33668805, 2021). "In addition, MORC4 recruits STAT3 to the MID2 promoter and drives MID2 expression in luminal A/B breast cancer cells, which enhances the chemoresistance of breast cancer, indicating that MORC4 may be a therapeutic target for luminal A/B breast cancer therapy." (PMID 34839357, 2021). "In addition, leptin-dependent activation of JAK1/2/STAT3/FAK/ERK/GSK3αβ signaling cascade in breast tumor cells enhanced the production of intercellular adhesion molecule 1 (ICAM-1), toward the development of breast cancer bone metastasis." (PMID 33562737, 2021). "Besides, although STAT3 mRNA showed no differenence between normal cohorts and patients, STAT3 mRNA positively correlated with the survival probability of breast cancer patients." (PMID 34335938, 2021). "As breast cancer is a heterogeneous disease which could be grouped into Luminal A, Luminal B, HER2-enriched, and Triple negative subtypes, we further explored the relationship of EZH2 and STAT3 expression with survival of patients in breast cancer subtypes." (PMID 34335938, 2021). "Meanwhile, combination of the STAT3 inhibitor and anti-PD-1 antibody synergistically improved T cells activation, CCL5 and IFN-γ releasing in the TME as compared toanti-PD-1 alone, and decreased tumor-infiltrating Tregs, therefore inhibiting the breast cancer progression and metastasis." (PMID 33957948, 2021). "In addition, induction of CTH expression by signal transducer and activator of transcription 3 (STAT3) signaling facilitates cell proliferation and migration in breast cancer, whereas induction of CTH expression by Wnt/β-catenin pathway stimulates cell proliferation in colon cancer." (PMID 34207284, 2021).
breast cancer (continued). "Importantly, STAT3 can act as a negative feedback regulator, and targeted inhibition of STAT3 can enhance the efficacy of radiotherapy for head and neck cancer, lung cancer, and breast cancer." (PMID 34504527, 2021). "Additionally, we detected the over-expression of the non-canonical Wnt/PCP pathway, which is involved in breast cancer progression, synergizing with the STAT3 pathway, contributing to its aggressiveness in both the stroma and the epithelium." (PMID 34282769, 2021). "In human breast cancer cells, MDA-MB-468, epidermal growth factor (EGF)-induced EMT is correlated with a transient elevation of cytosolic Ca2+ and accompanied by increased vimentin expression and phosphorylation of signal transducer and activator of transcription 3 (STAT3) markers of EMT." (PMID 34944940, 2021). "Furthermore, dendrosomal curcumin has been reported to exhibit a similar effect in a murine metastatic breast cancer model, increasing the level of M1-like macrophages while decreasing the level of M2-like macrophages in the TME through the downregulation of STAT3." (PMID 33572626, 2021). "As there has been no STAT3-targeted drug approved for clinical application, natural products which inhibit STAT3 to achieve the cytotoxic activity in breast cancer studies could be selected as a positive control, such as JSI124 (cucurbitacin I)." (PMID 34638708, 2021). "The expression level of phosphorylated ERK1/2 (p-ERK1/2) in breast cancer cells was remarkably increased in the DR-Exos-treated group compared with that of the control and DS-Exos-treated group, whereas the phosphorylation of Akt and STAT3 was not changed." (PMID 33879771, 2021). "Based on these data, we hypothesize that ASS1 expression restores arginine metabolism in M231-ADIR cells, whereas TREM1 expression stimulates AKT/mTOR/STAT3 and a CCL2 feed-forward loop to provide survival signals contributing to ADI resistance in breast cancer cells." (PMID 33664852, 2021). "Therefore, CYM-5478 should not affect Stat3/phospho-Stat3 expression in order for cisplatin to induce its chemotherapeutic effects in breast cancer cells." (PMID 31952197, 2020). "Knockdown of ANO1 in MCF-7 or T47D breast cancer cells resulted in a reduced tyrosine phosphorylation of EGFR (the site is not reported) and of STAT3 transcription factor in response to EGF, whereas overexpression of ANO1 in T47D cells increased phosphorylation EGFR and STAT3." (PMID 33250781, 2020). "In breast cancers, SOX2 is up-regulated by the transcription factor FOXO1 (Forkhead box protein O1), the long non-coding RNA SOX2OT (SOX2 overlapping transcript), and the EGFR/Stat3 signaling pathway in a paracrine manner involving tumor-associated macrophages." (PMID 33553286, 2020). "Hence, the contributions of STAT5 activation in HCC share certain similarities with breast cancer—STAT5 can act both as a tumour suppressor, in conditions where STAT3 is active in tumorigenesis, or as an oncogene to drive tumour aggressiveness in other instances." (PMID 32872372, 2020). "Finally, we discovered that inhibited expression of miR-337-3p and its downstream target STAT3 might regulate EMT and promote metastasis in breast cancer models suffering chronic stress." (PMID 32934214, 2020). "In human breast cancer, STAT3 expression was significantly higher in TNBC than that in non-TNBC." (PMID 32432040, 2020). "In addition, disruption of the IL6-STAT3 signaling pathway can overcome resistance to PI3K inhibitors, suggesting that combined blockade of STAT3 and PI3K signaling might be a more efficient therapeutic strategy for breast cancer." (PMID 32391382, 2020). "By extension this has large implications for STAT3 mediated signalling in ER positive and negative breast cancers in the potential promotion of invasion, metastasis and usage of lipids for metabolic maintenance of cancer promoting/tumour initiating populations of cancer stem cells." (PMID 32331320, 2020).
breast cancer (continued). "Furthermore, STAT3 did not alter the amounts of vaccine-derived CD103+ cDC1s in mammary tumors or TdLNs, as judged by equivalent numbers of CD45.2+Stat3fl/fl and CD45.2+Stat3∆/∆ CD103+ cDC1s detected in each site." (PMID 31947933, 2020). "AG490 inhibited STAT3 activation and exhibited anti-cancer effects such as inhibition of cell growth and induction of apoptosis via targeting of JAK2 in preclinical models of breast cancer, gastric cancer, pancreatic cancer, and gallbladder cancer, among others." (PMID 33521321, 2020). "One of the most prominent TF families in breast cancer is the signal transducers and activators of transcription (STAT) family, which is comprised of seven structurally similar and highly conserved members, namely, STAT1, STAT2, STAT3, STAT4, STAT5a, STAT5b and STAT6." (PMID 32111215, 2020). "Our results reveal that JAK2/PAK1 dysregulation inhibits the Stat3 signaling pathway and CSC formation, the PAK1/Stat3 complex regulates IL-6 gene expression, PAK1/Stat3 signaling regulates CSC formation, and PAK1 may be an important target for treating breast cancer." (PMID 31658701, 2019). "Indeed, approximately 50 % of TAMs express PD-L1 (data not shown) independent of Stat3 expression in the 4T1 mammary tumor model system, but it is still unclear how this can influence the anti-tumor immunity." (PMID 31581535, 2019). "Importantly, we confirm that OSM induces at least a 4-fold increase in IL-6 production from estrogen receptor-negative (ER−) breast cancer cells in a manner that is dependent on STAT3 signaling." (PMID 31007849, 2019). "Honokiol has been shown to target STAT3 to reduce its expression and phosphorylation in many cancer cells such as human glioblastoma, lung cancer, oral squamous cell carcinoma (OSCC), breast cancer, human epidermoid carcinoma, colorectal cancers, gastric cancer, and esophageal adenocarcinoma." (PMID 31877856, 2019). "Hence, identifying drugs that can inhibit IL-6/STAT3 signalling may present an opportunity to inhibit adipocyte-induced EMT and invasion in breast cancer cells." (PMID 31383893, 2019). "Moreover, breast cancer-derived exosomes are capable of inducing IL-6 secretion and a pro-tumoral phenotype (IL-6, IL-10, CCL2 production) in macrophages, partially via gp130/STAT3 signaling." (PMID 31480382, 2019). "Additionally, miR-21 links EMT and inflammatory signals (IL-6/STAT3/NF-κB-mediated signaling loop and activating the PI3K pathway) to confer resistance to trastuzumab and chemotherapy in HER2-positive breast cancer patients through downregulation of PTEN and programmed cell death 4 (PDCD4)." (PMID 31766744, 2019). "Furthermore, OSM induces STAT3 phosphorylation and IL-1β promotes p65 phosphorylation to synergistically induce IL-6 secretion in ER− MDA-MB-231 and to a lesser extent in ER+ MCF7 human breast cancer cells." (PMID 31007849, 2019). "Binding of transcription factors NF-κB and STAT3 to promoters of key proliferative genes such as cyclin D1 and c-Myc, in combination with ERα, provided the basis for estradiol-independent, non-canonical proliferation of ER+ breast cancer cells." (PMID 30736340, 2019). "RhoU down-regulation by silencing or treatment with JNK, SP1 or STAT3 inhibitors leads to impaired migration and invasion in basal-like MDA-MB-231 and BT-549 cells, suggesting that STAT3 and SP1 can cooperate to induce high RhoU expression and enhance breast cancer cells migration." (PMID 30654518, 2019). "Furthermore, subpopulations of breast cancer cells that are ALDH1 positive express higher levels of phosphorylated STAT3 (Tyr705) than cells that do not express this stem cell marker." (PMID 30542507, 2018). "We discovered that post-surgical WF contained factors that induced the enrichment of breast cancer cells with stem-like and tumor-initiating properties, and these phenotypes were specifically mediated by the activation of STAT3, but not by other STAT family members." (PMID 30231553, 2018).